RET (ret proto-oncogene)
Diseases named in the same sentence as RET in open-access papers (continued):
Sharing a sentence is not in itself a finding about the gene and the disease.
sarcoma (27 papers, 2012 to 2026). A usually aggressive malignant neoplasm of the soft tissue or bone. "This is the first report of successful targeted therapy with selpercatinib in RET-fusion-associated sarcomas." (PMID 36469155, 2023). "Recently, rearranged during transfection (RET)-fusion-associated sarcomas have been reported in a series of six cases." (PMID 36469155, 2023). "In this group, REarranged during transfection (RET) and rat sarcoma (RAS) mutation status were assessed by direct sequencing in the tumor tissues." (PMID 28676824, 2017). "The RET-fusion sarcoma has low mitotic activity, minimal lymphoplasmacytic infiltrate, and native glandular entrapment." (PMID 39064514, 2024). "We report an highly effective neoadjuvant and adjuvant treatment of a patient with a RET::TRIM33-fusion sarcoma with the selective RET inhibitor selpercatinib." (PMID 36469155, 2023). "Here, we describe a case of a sarcoma, associated with a RET::TRIM33-fusion gene with an exceptional response to a neoadjuvant therapy with the selective RET inhibitor selpercatinib." (PMID 36469155, 2023). "RET fusions were identified in three patients in the STS cohort – sarcoma NOS (n=2) and undifferentiated pleomorphic sarcoma (n=1) –, one patient in the bone sarcoma cohort (osteosarcoma), and one patient in the uterine sarcoma cohort (leiomyosarcoma)." (PMID 36741731, 2022). "Anlotinib (multi-target TKI that inhibits VEGFR, FGFR, PDGFR, KIT, and RET) was evaluated by a multiple-institution retrospective study in 48 patients with advanced sarcomas including 27 OS, eight ES, nine CS, and three chordomas." (PMID 36430263, 2022). "RET expression was significantly greater in patients with EMC relative to other types of sarcomas except for liposarcoma (p<0.0002)." (PMID 28423517, 2017). "Only RET expression was significantly greater in patients with EMC relative to other types of sarcomas excluding liposarcoma (p<0.0002, by student t-test)." (PMID 28423517, 2017). "Some well-established fusion genes have also been shown to be promiscuous, examples including MLL- in leukemias, EWS- in sarcomas, RET- in carcinomas and TMPRRS2- and ETV1-fusions in prostate cancer." (PMID 23119097, 2012). "Online Kaplan-Meier survival analysis further demonstrated the oncogenic role of RET in sarcoma." (PMID 31534554, 2019). "In a recent large study of sarcoma, CGP identified potentially actionable kinase fusions (including NTRK1‐3, ALK, BRAF, FGFR1‐4, RET, and ROS1) in 2.6% of patients." (PMID 38925616, 2024). "These included ALK, BRAF, FGFR1–4, NTRK1–3, RET, and ROS1 kinase fusions in a wide range of sarcoma histologies, including IMT (62.1%), MPNST (4.9%), UPS of bone (4.3%), extraskeletal osteosarcomas (4%), UPS (3.6%), sarcoma NOS (3.8%), and LMS (1.9%)." (PMID 35705558, 2022). "For instance, based on the interquartile range, some cancers, such as liver hepatocellular carcinoma (LIHC), sarcoma (SARC) and COADREAD, had a widespread range of RET expression, while others—like TGCT, THCA and glioblastoma multiforme (GMB)—did not." (PMID 35978072, 2022). "Sorafenib, regorafenib, lenvatinib, and anlotinib, all of which have activity against VEGFR, PDGFR, RET, c-KIT and FGFR, and cabozantinib, which has a different target profile (VEGFR, MET, AXL, and RET), have all shown some clinical benefit in sarcoma." (PMID 34944614, 2021). "The expression levels of sunitinib targeted-kinases were measured by transcriptome sequencing for PDGFRA/B, KIT, RET, FLT1(VEGFR1), KDR (VEGFR2), and FLT4(VEGFR3) for patient cohort with EMC and other sarcoma histologies." (PMID 28423517, 2017).
sarcoma (continued). "We next examined the expression of 19 genes in different bone-related sarcomas using The Cancer Genome Atlas (TCGA) database and found relatively high HSPA5 and ATF4 mRNA levels in tumor tissues and significantly low CBLC and RET expression levels." (PMID 31534554, 2019). "For example, not all BCOR-rearranged sarcomas are positive for BCOR on IHC, and a subset of IMTs are negative for ALK on IHC because they harbor alternative ROS1 or RET gene fusions instead of an ALK fusion." (PMID 38137051, 2023).
neurofibromatosis type 1 (22 papers, 2012 to 2025). A clinically heterogeneous, neurocutaneous genetic disorder characterized by cafe-au-lait spots, iris Lisch nodules, axillary and inguinal freckling, and multiple neurofibromas. "In particular, mutations of VHL, NF1 and RET cause well characterized cancer susceptibility syndrome (von Hippel Lindau, Neurofibromatosis Type 1 and MEN2, respectively)." (PMID 26084817, 2015). "The “kinase signal type” is associated with systemic hereditary diseases such as MEN2A/2B (RET mutation) and neurofibromatosis type 1 (NF1 mutation)." (PMID 33193100, 2020). "A genetic test for RET, Von Hippel-Lindau (VHL), Neurofibromatosis type 1 (NF1), and of the genes coding for the different subunits of the succinate dehydrogenase (hereditary paraganglioma syndromes) is suggested in familial PCC to obtain a precocious diagnosis." (PMID 24267584, 2013). "In addition, in young patients without a RET germline mutation, a careful clinical evaluation with a consideration of germline NF1 gene analysis is ideal to exclude Neurofibromatosis type 1 (NF1)." (PMID 38655100, 2024). "Although rare, co-occurrence of neurofibromatosis type I and MTC or its precancerous condition C-cell hyperplasia has been documented in previous literatures, several of which have identified NF1 with or without RET germline mutations by peripheral blood DNA sequencing." (PMID 36344509, 2022).
colon carcinoma (19 papers, 2012 to 2024). "In particular, the identification of gain-of-function RET variants in a subset of colon cancer, as described here, has led to the identification of a small subset of patients potentially treatable with RET inhibitors." (PMID 29665843, 2018). "The colon cancer model Co11291-273 is characterized by a RET mutation." (PMID 34885128, 2021). "We investigated whether the RET variants identified in colon cancer patients are able to stimulate anchorage-dependent proliferation in HEK293 cells." (PMID 29665843, 2018). "In this manuscript, we have investigated whether the RET variants identified in colon cancer patients are able to confer pro-tumorigenic properties to epithelial cells." (PMID 29665843, 2018). "In addition, METex14del occurs exclusively to ALK, ROS1, NTRK1, NTRK3 or RET fusions indicating METex14del is likely a driver mutation and defines a unique molecular subset of gastric and colon cancers." (PMID 26375439, 2015). "We realize that additional molecular or histology markers should be considered in combination to RET methylation in order to enhance the predictive value for accurate and robust identification of high-risk stage II colon cancer patients or that other markers might better predict prognosis." (PMID 27118999, 2016). "Although RET fusions were rare variants in CRC, one study found that more than two-thirds of the patients with right hemizygous colon cancer, RAS/BRAF wt, and MSI-H in CRC carried RET gene fusions." (PMID 37927605, 2023). "PI3K, mTOR (everolimus), and RET (regorafenib) inhibition seem to be synergistic with EGFR (cetuximab) inhibition in selected colon cancers with those activated pathways." (PMID 34885128, 2021). "Interestingly, ARTN, NRTN, GFRα1, and GFRα3 are found in colon tumors, potentially arising from gut nerves or associated with chronic inflammation of the intestine, which increases cancer risk, suggesting a subset of RET-expressing colon tumors may be responsive to GFL stimulation." (PMID 30666215, 2018). "Yet, the identification of gain-of-function RET variants in colon cancer patients provides novel data for the involvement of this RTK in the development of colon cancer and identifies RET as a novel putative target for targeted therapy." (PMID 29665843, 2018). "Expression of RET protein and the levels of its phosphorylation at residues Y905 and Y1062 were assessed in colon cancer and the corresponding normal mucosa of patients CC12 and CC20 using immunofluorescence." (PMID 29665843, 2018). "In the current study, we analyzed the RET promoter CpG island methylation of 241 stage II colon cancer patients by direct methylation-specific PCR (MSP), nested-MSP, pyrosequencing, and methylation-sensitive high-resolution melting (MS-HRM)." (PMID 27118999, 2016). "An activating RET fusion was identified in a patient with resected colon cancer." (PMID 39590164, 2024). "Here we show that Pz-1 is a potent inhibitor of TRK kinases as well, that is active against several RET and TRKA mutants that are resistant to other TKIs and that is effective in xenografts of human MTC, lung and colon carcinoma cells driven by RET or TRKA oncogenes." (PMID 34373541, 2021). "Accordingly, the active RET mutant detected in colon cancer patients (G533C) may resemble those described in MEN2A patients, of which the C634R is the prototype." (PMID 29665843, 2018). "We observed hyper-methylation of RET, a tumor suppressor gene methylated in 63% of colon cancers." (PMID 28257124, 2017). "Therefore, tumor suppressor activity of RET in the colon cancer is suggested." (PMID 33906292, 2021). "Structural variations were relatively infrequently to find three cases of CDKN2A, ERBB2 and EGFR amplification and single one RET-NCOA fusion in a young patient with sporadic, left colon cancer (MSI-S)." (PMID 26909603, 2016).
Hypertension (18 papers, 2008 to 2026). The presence of chronic increased pressure in the systemic arterial system. "Even the better tolerated RET inhibitor, selpercatinib, has a risk for hypertension and elevation of liver transaminases, among other adverse effects." (PMID 39076377, 2024). "Common AEs linked to RET inhibitors consist of fatigue, hypertension, dry mouth, low red blood cell count, oedema, reduced white blood cell count, and increased ALT and AST levels." (PMID 39372206, 2024). "Taken together, the increase in CD47 seems to be responsible for the development of RET inhibitor-associated hypertension." (PMID 36768635, 2023). "Careful neuro−cognitive and growth−plate monitoring is essential because paediatric TRK or RET inhibitor trials report mostly grade−1/2 neuropathy, transient liver enzyme rise, weight gain, physeal thickening and occasional hypertension—usually reversible with dose adjustment." (PMID 41142827, 2025). "The possible explanations could be that both drugs inhibit VEGFR at the clinical doses administered or that RET inhibition itself can mediate hypertension." (PMID 39199650, 2024). "However, since MKIs were not designed to specifically target RET, their use is associated with low clinical benefit and significant off-target side effects, such as nausea, diarrhea, rash, and hypertension, in some patients with RET-activated cancers." (PMID 38201566, 2023). "The underlying mechanisms for RET-inhibitor-associated hypertension are still not clarified." (PMID 36768635, 2023). "Thus, CD47 upregulation may also be important in the development of hypertension with RET inhibitors." (PMID 33793337, 2021). "Concerning the multi-TKIs used in the RET fusion NSCLC, hypertension is most prominent in vandetanib and lenvatinib compared to cabozantinib." (PMID 39199650, 2024). "In treatment-naïve patients with RET fusion–positive NSCLC who received pralsetinib (n = 116), the most common grade 3–4 TRAEs were neutropenia (18%), hypertension (10%), increased blood creatine phosphokinase (9%), and lymphopenia (9%)." (PMID 38201460, 2023). "According to prescribing information, treatment with RET inhibitors should not be initiated in patients with uncontrolled hypertension." (PMID 38118420, 2023). "Parallel efforts are refining highly selective RET inhibitors with favourable paediatric safety profiles and negligible off-target VEGFR blockade, a characteristic that may attenuate dose-limiting hypertension and thrombotic events often observed with multikinase agents." (PMID 41142827, 2025). "In this group of 233 patients with RET fusion–positive NSCLC, common treatment related adverse events (TRAE) of grade 3 or higher were neutropenia, (18%), hypertension (11%), and anemia (10%); there were no treatment-related deaths in this population." (PMID 38201460, 2023).
anaplastic thyroid carcinoma (17 papers, 2000 to 2025). "Although RET fusions are uncommon in anaplastic thyroid cancer (ATC), they are associated with aggressive tumor behavior, including increased rates of lymph node and distant metastases." (PMID 40363930, 2025). "The RET/PTC rearrangements and mutations in the RET gene are genetic events that are considered relatively rare in anaplastic thyroid carcinoma (ATC)." (PMID 39744583, 2025). "CDKN2A loss has been reported in anaplastic thyroid cancer, but the frequency of this genetic alteration in RET-rearranged cancer is unknown." (PMID 35510953, 2022). "These markers directly guide FDA-approved targeted therapies, including selpercatinib for RET-specific disease and dabrafenib plus trametinib for BRAF V600E-mutated anaplastic thyroid cancer." (PMID 41595456, 2025). "MAPK15 is expressed at high levels in anaplastic thyroid carcinoma cells, and can be activated by RET/PTC3, an activated form of the RET proto-oncogene." (PMID 26035356, 2015). "Activation of the RET signaling pathway can lead to uncontrolled cell growth and prolonged survival of cancer cells, thereby contributing to the development and progression of anaplastic thyroid carcinoma." (PMID 39744583, 2025). "Recurring non-canonical activating mutations included RET E511K (n = 3) which was identified in patients with anaplastic thyroid cancer, endometrial adenocarcinoma, and Merkel cell carcinoma." (PMID 37627175, 2023). "NRP2 expression is significantly increased in all the PTC and follicular thyroid carcinoma samples derived from TRK, RET/PTC3, and N-ras mice and in the anaplastic thyroid carcinoma samples derived from the simian virus 40 large T mice." (PMID 26030152, 2015).
neuroendocrine tumor (17 papers, 2013 to 2025). "Medullary thyroid carcinoma (MTC) is a neuroendocrine tumor mainly caused by mutations in the RET proto-oncogene." (PMID 35162987, 2022). "MTC is a rare neuroendocrine tumor originating from parafollicular C cells of the thyroid and associated with mutations in the proto-oncogene REarranged during Transfection (RET)." (PMID 28658345, 2017). "In neuroendocrine tumors, mutation of the RET proto-oncogene was identified as the causative gene for human papillary and medullary thyroid carcinoma, as well as for neuroendocrine small cell lung cancers, and early clinical trials of Ret inhibitors show encouraging results." (PMID 32252363, 2020). "Long-term clinical follow-up include genetic background analysis such as SDHB, SDHD, VHL, and RET, required in view of the metastatic potential of this rare neuroendocrine tumor." (PMID 41426338, 2025). "Germline RET mutations cause multiple endocrine neoplasia type II, leading to the occurrence of medullary thyroid cancers (MTC) and neuroendocrine tumors such as pheochromocytomas." (PMID 39139787, 2024). "While models for genes of cluster 2 PPGL (RET, NF1, and TMEM127) have been studied since 1992, these models are suboptimal as they are generally associated with development of additional unrelated non-neuroendocrine tumors." (PMID 36428741, 2022). "Indeed, MTC is a neuroendocrine tumor and MZ‐CRC‐1 cells harbor the multiple endocrine neoplasia type 2B RET‐M918T mutation, transmitted in this disease as an autosomal dominant trait." (PMID 28453190, 2017). "Interestingly, unlike RET rearrangements, activating RET point mutations are extremely rare outside of the neuroendocrine tumors." (PMID 30666215, 2018).